IL13 (interleukin 13)
Diseases named in the same sentence as IL13 in open-access papers (continued):
Sharing a sentence is not in itself a finding about the gene and the disease.
tumor (continued). "Interestingly, all these GEP class-associated cytokines (PDGF-AB/BB, MCP-3/CCL7, TNF-β, G-CSF, IL-13, and IL-3) were also among the tumor size-correlated cytokines." (PMID 37509362, 2023). "Each of the IL13(E12Y)-CAR T cell variants were also able to efficiently kill IL13Rα2-expressing tumor cells in a 48-hour coculture at E:T ratios of 1:4, although the third-generation IL13-28BBζ CAR displayed slightly reduced killing potency against the GBM line PBT030-2." (PMID 36968221, 2023). "In a model of sporadic CRC, genetic IL-13 deficiency significantly reduced tumour burden, and adoptive transfer of IL-13+ ILC2s compared to IL-13– ILC2s led to enhanced MDSC activation and downstream suppression of anti-tumoural IFNγ+ CD8+ T cells and Th1 cells." (PMID 37455828, 2023). "Th2 cell was proposed to promote tumor progression through the secretion of cytokines interleukin (IL)‐4, IL‐6, IL‐10, and IL‐13 to activate tumor‐associated M2 macrophages, and which was found to be a risk factor of male patients in SARC, LUAD, KIRP, PAAD, KIRC, and LIHC (HR > 1, Wald P < 0.05)." (PMID 35229456, 2022). "Generally, M1-polarized macrophages exert anti-tumor effects through eliminating and destroying phagocytosed tumor cells, while M2-like macrophages, activated by IL-4, IL-10 and IL-13, resemble tumor-associated macrophages (TAMs), which promote tumor progression though immunosuppressive functions." (PMID 35807802, 2022). "In vivo alterations of the tumor immune environment involved fewer protumorigenic tumor-associated macrophages (TAMs) and MDSCs due to the suppression of IL-4, IL-13, and CXCL1 expression, and elevated infiltration by antitumor CTLs and NK cells attracted by elevated CXCL9 and CXCL10 levels." (PMID 35499071, 2022). "Tumor-associated macrophages (TAMs) are the predominant immune cell types with immunosuppressive M2 polarized phenotypes that secrete tumor cytokines (IL-4, IL-10, and IL-13)." (PMID 36479071, 2022). "IL‐13 favours M2 polarization of tumour‐associated macrophages." (PMID 35344301, 2022). "Apoptotic cell clearance via efferocytosis polarizes tumor-associated macrophages (TAM) to adopt pro-tumor ‘M2’ wound-healing phenotypes which, by secreting cytokines such as IL-4, IL-10, IL-13 and TGF-β1, further educate Th0 or Th1 CD4 T cells towards a Th2 phenotype." (PMID 34359823, 2021). "Thus, when blood monocytes attracted to the TME differentiate into tumour-associated macrophages (TAM) they can provide either anti-tumour (M1) or tumour-promoting activity (M2) as driven respectively by the local levels of IFN gamma versus IL-4/IL-13." (PMID 34202255, 2021). "In this model, activation of cancer cells carrying the mutated KRAS by IL-4 and IL-13, which were secreted by the Th2 cells present in the tumor microenvironment, triggered the JAK1-STAT6-MYC pathway that in turn activated glycolysis crucial for tumor progression." (PMID 33042121, 2020). "Interestingly, these unique DEGs are annotated with GO biological process terms associated with IFNγ regulation and secretion (GO:0032609), IL-13 secretion (GO:0030101), and immune response to tumor cell (GO:0002418)." (PMID 32093192, 2020). "Like in AIT, IgG4 formed in tumor and tumor stroma is associated with chronic antigen challenge and with the Th2 cytokines IL-4 and IL-13, in combination with IL-10, released by Treg cells and M2-like macrophages in particular but also by the tumor cells themselves." (PMID 32708690, 2020). "IL-4 and IL-13 produced by human T helper 2 (Th2) cells, basophils, and T follicular helper cells (Tfh) induce alternative (M2) activation of macrophages and tumor-associated macrophages." (PMID 31412566, 2019). "Also, the abundance of IL-13Rα2 on glioblastoma cells was clinically explored by designing an IL-13-linked toxin to kill tumor cells in a phase I clinical trial." (PMID 30759882, 2019).
tumor (continued). "IL-13/IL-13R interaction in breast cancer and cholangiocarcinoma cells in association with recruitment and induction of TGFβ-producing MDSCs and Treg has been reported to induce tumor cell growth and migration, and tumor immune escape." (PMID 29675018, 2018). "TAMs are typically associated with an M2-like polarization state caused by tumour-derived lactic acid or secretion of immunosuppressive cytokines such as IL-4, IL-10, and IL-13 from different cells in the tumour microenvironment or B cell-derived immunoglobulins." (PMID 28210073, 2017). "Tumor stroma IL-13 density could only identify low-risk group and high-risk group at TNM stage II and III." (PMID 26771842, 2016). "Indeed, IL-4 and IL-13 are now considered key players in alternative macrophage generation, including tumour associated macrophages (TAMs)." (PMID 25951175, 2015). "Similarly, deficiency of IL-13, mainly produced by tumor-infiltrating NKT cells, was shown to result in a dominance of M1-type TAMs and resistance to metastasis." (PMID 24723924, 2014). "Moreover, blocking IL-13 prevented the rapid tumor growth associated with the addition of the CD4+ T cells to the model, suggesting that in this model CD4+ T cells are polarized to produce IL-13 and promote tumor development." (PMID 21281484, 2011). "Additionally, in the humanized mouse model, anti-TSLP controlled tumor development and was associated with reduced capacity of tumor infiltrating T cells to produce IL-13." (PMID 21281484, 2011). "IL13-PE (0.5 mg/mL, 0.75 mL/h over 96 hours) was administered via 2–4 intraparenchymal catheters placed in areas at greatest risk for infiltrating disease or in the vicinity of any residual, solid, contrast-enhancing disease 2–7 days after tumor resection." (PMID 22069569, 2010). "Indeed, Th2 cytokines and IL-13 in particular are strongly associated with stroma deposition, which is a peculiar feature of PC and is potentially involved in tumor progression, while IFN-γ suppresses collagen synthesis by fibroblasts." (PMID 19798410, 2009). "Tumour-associated macrophages are derived from circulating monocytes and are activated macrophages of the polarised type II (type II or M2 macrophages) induced by IL-4, IL-13 (M2a) or IL-10 (M2c) and glucocorticoid hormones." (PMID 16832418, 2006). "Since CD4+ Th2 cells and Th2 cytokines such as interleukin-4 (IL-4), IL-5, IL-6, IL10 and IL13 were thought to be associated with immunosuppressive contexture and tumor-promoting effects, we believed that LMNB1 could be considered as a biomarker of immunosuppressive microenvironment." (PMID 35241075, 2022). "One possible explanation is that IgG4 produced in tumor microenvironment and stroma may be associated with chronic antigen challenge associated with Th2 cytokines including IL-4, IL-10, and IL-13, which causes inappropriate host immune tolerance against malignancies and tumor progression." (PMID 33920932, 2021). "The increased presence of IL-13 in the urine of BC patients was probably due to the increased inflammatory process associated with cancer, which includes local changes in the urinary bladder or may have its origin in the tumor itself." (PMID 33343662, 2020). "Importantly, IL-4 and IL-13 are closely related to type 2 immune response-associated cytokines that induce the alternatively activated phenotype of macrophages and are known to play a prominent role in promoting tumor progression." (PMID 33352852, 2020). "Consequently, IL-4/IL-13 blockade may theoretically reduce tumor risk." (PMID 40843371, 2025). "The other is the alternatively activated M2-like macrophage, induced by IL-13 and IL-4, which plays a role in supporting tumor growth, tissue remodeling, and promoting tumor progression." (PMID 40028336, 2025). "Collectively, these data demonstrate that there is a subset of activated ieILC1-like NK cells capable of producing IL-13 upon tumor cell stimulation." (PMID 40114916, 2025).
tumor (continued). "Conversely, in certain tumor contexts, IL-4 and IL-13 contribute to the activation and survival of cytotoxic T lymphocytes and natural killer (NK) cells, supporting immune surveillance against malignant cells." (PMID 40981274, 2025). "ILC2s promote tumor progression by secreting IL-4 and IL-13, which activate the IL-4Rα–STAT6 signaling pathway." (PMID 40497988, 2025). "ILC2s, dependent on the GATA-binding protein 3 (GATA3) transcription factor for development, exert anti-tumor activity by secreting type 2 cytokines such as IL-4 and IL-13 in the tumor microenvironment, influencing tumor prognosis." (PMID 40661781, 2025). "The full inhibitory function of MDSC in tumor-conditioned mice requires the coordinated action of IL-13 and IFNα released by cells in an autocrine manner." (PMID 40948749, 2025). "In contrast, the M2 phenotype, characterized by the expression of cytokines such as interleukin-4 (IL-4), interleukin-13 (IL-13), and IL-10, exhibits tumor-promoting and angiogenic functions." (PMID 40918147, 2025). "IL-13 plays a central role activating a Th2 response and inducing M2-like Mɸ polarisation, both critical factors in diminishing the efficacy of anti-tumour immunity." (PMID 39965288, 2025). "The cytokines IL-33 and IL-13, central players in type 2 immune responses, play significant roles in promoting an immunosuppressive tumor microenvironment that favors cancer progression." (PMID 40761291, 2025). "IL-13 has also been reported to suppress anti-tumour immunity by inhibiting IFN-γ secretion and the activity of cytotoxic T lymphocytes." (PMID 39325360, 2025). "IL-4 and IL-13 drive a unique “Mac-e” state that is characterized by immunosuppressive genes and reparative M2-like states and related to enhancing tumor cell proliferation and suppressing CD8+ T cell activation." (PMID 41467185, 2025). "Conversely, M2-like TAMs are driven by IL-4, IL-13, and IL-10, and promote tumor progression by releasing immunosuppressive factors (PGE2, TGF-β, IL-10), and pro-angiogenic mediators (FGF, PDGF, VEGF)." (PMID 41383623, 2025). "IL-13-expressing ieILC1-like NK cells were identified among tumor infiltrating lymphocytes expanded from patient HNSCC tumors, in support of their in vivoexistence in primary tumors." (PMID 40114916, 2025). "In the tumor site, release of cytokines, including IL-13 and IL-4, induces polarization toward M2-type macrophages." (PMID 40969416, 2025). "Activated MCs release cytokines such as IL-6, TNF-α, and IL-13, which are known to promote transcriptional repression and DNA methylation at tumor suppressor loci via STAT3 and NF-κB signaling cascades." (PMID 40871387, 2025). "Several studies identified proteins such as Cyfra 21-1, Cathepsin B, AKR1B10, IL-10, IL-13, and TNF-α as being associated with tumor burden, histological grade, or recurrence risk." (PMID 41149126, 2025). "Among the evaluated cytokines in the early stage of MC4-L2 tumors, only a rise in IL-10 expression was detected; after tumor progression, IL-13 and IL-22 were overexpressed in addition to IL-10." (PMID 39877637, 2025). "On the other hand, ILC2 produces effector cytokines such as IL-5, IL-9, and IL-13, which generally have a pro-tumor effect." (PMID 40136347, 2025). "Although most cytokines changed in the tumor induced by BNT162b2 play a role in tumor-killing, there was a significant decrease in intratumoral IL-4, and significant increases in intratumoral IL-13 and peripheral IL-17A." (PMID 39743545, 2025). "In our data, we find that IL-13+ ieiLC1-like NK cells express markers of cytotoxicity like CD107a and higher levels of IL-13 in HNSCC were associated with lower pathologic stage, supporting a possible anti-tumor role for this cell subset." (PMID 40114916, 2025). "By directly suppressing Th1 cytokines and promoting MF tumor cell survival and proliferation (often in conjunction with IL-13), IL-4 enables immune evasion, chronic inflammation, and fibrosis in the skin." (PMID 40864740, 2025).
tumor (continued). "Evaluating the equilibrium between IFN-γ and anti-inflammatory cytokines (IL-4 + IL-10 + IL-13) revealed tumor progression is accompanied by an increased inflammatory balance in 4T1 tumors (P=0.0004), in contrast to MC4-L2 tumors." (PMID 39877637, 2025). "With these carboxylic acid-modified derivatives in hand, we investigated their impact at 10 μM on ARG1 and NOS2 mRNA expression in RAW 264.7 cells pre-stimulated with IL-4/IL-13 to evaluate the effects on the pro-tumor phenotype of macrophages." (PMID 40430260, 2025). "By contrast, Th2 cells support humoral responses via IL-4, IL-10, and IL-13, suppressing Th1-mediated responses and fostering an immunosuppressive tumor microenvironment." (PMID 41176307, 2025). "IL-13 interacts with its high-affinity receptor IL-13Rα2, inhibiting tumor cell apoptosis and resulting in poor tumor prognosis." (PMID 39934258, 2025). "IL‐13 belongs to the IL family of inflammatory regulatory factors and plays multiple roles in tumors, including promoting tumor cell proliferation and invasion, as well as suppressing immune responses." (PMID 41179703, 2025). "Such macrophages, also secreting immunosuppressive cytokines and chemokines, including IL‐10, IL‐13, and TGF‐β, contribute to immunosuppression and tumor progression and have also been associated with poor prognosis in patients with PDAC." (PMID 40736369, 2025). "Among Th subsets, Th1 cells mediate cytotoxicity via interferon-gamma (IFN-γ), while Th2 and Th17 cells, through IL-4, IL-13, and IL-17, support tumor progression." (PMID 41383623, 2025). "MφU-SNFIB-MAA-CIT- stimulated HCAECs exhibited upregulation of tumor microenvironment pathways, IL-4 and IL-13 signaling, inflammation signaling, and fibrosis signaling, with concurrent downregulation of IL-10 signaling pathways." (PMID 41296447, 2025). "Research revealed that a tandem configuration of IL13 and EphA2 scFv demonstrated that the IL13-anti-EphA2 TanCAR showed significantly enhanced anti-tumor efficacy compared to single CAR-T cells, in both in vitro and in vivo settings." (PMID 40861448, 2025). "TAM polarization toward the M2 phenotype, driven by IL-4 or IL-13, dampens anti-tumor T cell responses and enhances tumor-promoting processes including angiogenesis, proliferation, and invasion." (PMID 41058699, 2025). "For example, studies suggest that tumor-promoting Th2 cells exhibit high levels of IL-10 and TGF-β, whereas Th2 cells with elevated expression of IL-3, IL-5, and IL-13 demonstrate anti-tumor immunity." (PMID 40070825, 2025). "Th2-polarized CD4+ T cells produce cytokines (e.g. IL-4, IL-13) that can dampen Th1 responses and impair the function of cytotoxic T lymphocytes, thereby weakening the immune system’s ability to attack tumor cells." (PMID 41403933, 2025). "In ovarian cancer, it has shown promise by targeting the tumor microenvironment, specifically by suppressing the polarization of macrophages into the M2 pro-tumor phenotype, a shift usually triggered by interleukin IL-4 and IL-13 exposure." (PMID 40330466, 2025). "Tumor-derived signals promote macrophage polarization toward a pro-tumoral M2-like phenotype, supported by IL-4, IL-13, IL-10, TGF-β, hypoxia, immune complexes and tumor metabolites." (PMID 41230456, 2025). "With the known roles of IL-13 in cancer cell growth dynamics and immunoregulation, the identification of this subset within tumor microenvironments presents a potential target for therapeutic manipulation." (PMID 40114916, 2025). "ieILC1-like NK cells stimulated with K562 tumor cells secreted more IL-13 than unstimulated ieILC1-like NK cells." (PMID 40114916, 2025). "Expression of the differentiation marker IVL was increased after FOXM1 knockdown, while expression of basal marker tumor protein p63 (TP63) was decreased after knockdown even in the setting of IL-13 stimulation." (PMID 40501685, 2025).
tumor (continued). "By analyzing gene expression in GBM PNZ and tumor cells under ischemic conditions, our studies found that IL-4 and IL-13 signaling are the top-activated pathways." (PMID 39805854, 2025). "We also confirmed that treatment with a neutralizing antibody against IL-13 led to reduced tumor size, proliferation, and metaplasia in APP mice." (PMID 40761291, 2025). "ILC2s secrete type 2 cytokines, including IL-5, IL-13, IL-9, and amphiregulin, which can promote tumor growth." (PMID 40497988, 2025). "In the tumor microenvironment, IL-4 and IL-13 also polarize macrophages toward an M2 phenotype, which supports tumor growth and suppresses anti-tumor immunity." (PMID 40981274, 2025). "Th2 cells are a subset of CD4+T cells that promote tumor progression by secreting cytokines such as IL-10 and IL-13 to enhance angiogenesis and inhibit the cytotoxic effects of CD8+ T cells." (PMID 41040664, 2025). "IL-13 has been described as a potential predictive biomarker for cancer treatment, promoting tumor cell proliferation, invasion, and metastasis development." (PMID 40247153, 2025). "Studies have shown that in the tumor microenvironment, M2 macrophage polarization is regulated by various cytokines such as IL-4, IL-13, and the STAT6/C/EBPβ signaling pathways." (PMID 40433361, 2025). "Th2 cells produce interleukin (IL)-4 and IL-13, which inhibit cytotoxic T-cell function and diminish anti-tumor immune responses." (PMID 40740231, 2025). "IL-4’s anti-tumour effects are primarily mediated through eosinophils and macrophages, whereas IL-13’s anti-tumour activity is reported to be mediated by neutrophils and macrophages." (PMID 39325360, 2025). "Historically, Th2-polarized responses were thought to dampen Th1-mediated cytotoxicity and favor tumor growth by skewing immunity toward interleukin (IL)-4/IL-13-driven humoral pathways." (PMID 40428397, 2025). "There was interestingly lower IL-13 expression in tumour samples relative to healthy brain (1.76-fold decrease, mean LFC=-0.81 ± 0.29; p = 0.04, 95% CI=-1.58 to -0.04)." (PMID 41034696, 2025). "Few studies addressed the role of MCs in PDAC and reported their impact on angiogenesis and tumor cell migration predominantly via the release of Il13, which was among the top up-regulated factors released by MCs upon IL33-dependent stimulation." (PMID 38942797, 2024). "In contrast, M2 macrophages generate IL-13, IL-10, and other factors that foster tumor development and enhance the invasive capabilities of tumor cells." (PMID 39290709, 2024). "Briefly, as previously reported, the murine IL13Rα2-CAR T (mCAR T) consists of the murine IL13 tumor-targeting domain, murine CD8 hinge (mCD8h), murine CD8 transmembrane domain (mCD8tm), murine 4-1BB costimulatory domain (m4–1BB), and murine CD3 zeta (mCD3ζ)." (PMID 38994929, 2024). "Conversely, M2 macrophages, which play a role in tissue repair and tumor progression, are polarized by factors such as interleukin-4 (IL-4) and interleukin-13 (IL-13)." (PMID 39766056, 2024). "For instance, CD4+ Th-2 cells, innate lymphoid cells (ILCs)-2- and T-reg lymphocytes that produce IL-4, IL-13 and IL-10 can sustain the formation of M2-like macrophages with a pro-tumor phenotype." (PMID 38426089, 2024). "On one hand, there is now considerable evidence implicating ILC2s in the tolerogenic processes related to tumour immune evasion, and produce large amounts of IL-13, IL-5, and IL-4." (PMID 38172434, 2024). "IL-4 and IL-13, as well as IL-10, have been demonstrated to play important roles during primary tumor progression in mouse models of cancer." (PMID 39599846, 2024). "M2 macrophages can be activated by interleukin (IL)-4 and IL-13.During carcinogenesis, macrophages initially exhibit an M1-like polarization with anti-tumor properties, leading to enhanced elimination of tumor cells." (PMID 39100676, 2024).